PROS1 (protein S)
Diseases named in the same sentence as PROS1 in open-access papers (continued):
Sharing a sentence is not in itself a finding about the gene and the disease.
venous thromboembolism (23 papers, 2006 to 2025). Occlusion of the lumen of a vein by a thrombus that has migrated from a distal site via the blood stream. "Studies have shown that inherited thrombophilic disorders—such as Factor V Leiden mutation and deficiencies in protein C and protein S—are associated with venous thromboembolism in children." (PMID 40852411, 2025). "Clinical manifestations of protein S deficiency include an increased risk of venous thromboembolism (VTE), purpura fulminans in neonates, and warfarin-induced skin necrosis." (PMID 41393758, 2025). "Inherited antithrombin, protein C, and protein S deficiency increase the risk of venous thromboembolism." (PMID 39075507, 2024). "Inherited antithrombin (AT), protein C (PC) and protein S (PS) deficiency increase the risk of venous thromboembolism (VTE)." (PMID 39075507, 2024). "A retrospective study has shown that annual incidences of a first recurrence after the first episode of venous thromboembolism were 8.4% in protein S deficient patients." (PMID 35742044, 2022). "Patients with hereditary protein S deficiency have a high risk of venous thromboembolism recurrence." (PMID 35742044, 2022). "Protein S (PS) deficiency is a risk factor for venous thromboembolism (VTE) and can be caused by variants of the gene encoding PS (PROS1)." (PMID 34729451, 2021). "Risk factors like low CD4 cell count, especially in the presence of clinical acute immunodeficiency syndrome (AIDS), protein S deficiency, and protein C deficiency, have demonstrated the strongest association with venous thromboembolism." (PMID 32704356, 2020). "Patients with a protein S deficiency are prone to recurrent episodes of venous thromboembolism (VTE)." (PMID 33154484, 2020). "Protein S-K196E mutation (Pros1E/E) is a race-specific genetic risk factor for venous thromboembolism." (PMID 28686706, 2017). "In a Spanish study of 2132 consecutive unselected patients with venous thromboembolism, 7.3 percent had protein S deficiency." (PMID 16968541, 2006). "In a Spanish study of 2132 consecutive unselected patients with venous thromboembolism 12.9 percent had an anticoagulant protein deficiency (7.3 percent with protein S, 3.2 percent with protein C, and 0.5 percent with antithrombin)." (PMID 16968541, 2006). "Moreover, previous research has demonstrated that protein S deficiency is associated with a tenfold increase in the risk of venous thromboembolism." (PMID 38414076, 2024). "Protein S (PS) deficiency is widely recognized for its connection to venous thromboembolism risk." (PMID 38292964, 2023). "Protein S deficiency usually manifests clinically as venous thromboembolism (VTE)." (PMID 24594283, 2014). "In recent years, genetic analyses of congenital deficiencies of three anticoagulant proteins, antithrombin, protein C (PC) and protein S (PS), in East Asian patients with venous thromboembolism (VTE) have greatly increased." (PMID 27766051, 2016). "Results of protein C and protein S testing performed at diagnosis and on repeat testing after discontinuing anticoagulation therapy in patients with venous thromboembolism." (PMID 20482785, 2010). "Our results provide evidence that PROCR and DNAJC6 might play a role in protein C and free protein S plasma levels in the population studied, warranting further investigation on the role of these loci in the etiology of venous thromboembolism and other thrombotic diseases." (PMID 22216198, 2011).
pulmonary embolism (22 papers, 2006 to 2026). The obstruction of the pulmonary artery or one of its branches by an embolus, sometimes associated with infarction of the lung. "We report the case of a 32-year-old male patient who presented with mesenteric venous thrombosis and pulmonary embolism caused by a heterozygous missense mutation in PROS1, c.683G>A (p.Cys228Tyr) during the COVID-19 pandemic." (PMID 40771767, 2025). "Protein S deficiency caused by mutations in the PROS1 gene is the genetic basis for this patient's pulmonary embolism." (PMID 39465133, 2024). "Deficiencies in PROS1 in humans lead to a variety of blood clots (e.g., strokes, DVTs, pulmonary embolisms)." (PMID 36851756, 2023). "In previous studies a missense PROS1 mutation (Gly222Arg) has been identified in a patient with pulmonary embolism, which causes PS activity to decrease to 5.0%." (PMID 34496879, 2021). "A 13-year-old male that developed deep vein thrombosis (DVT) and pulmonary embolism following pneumonia caused by Mycoplasma pneumoniae was reported; however, protein S deficiency and transient lupus anticoagulant were underlying risk factors." (PMID 24744650, 2012). "We investigated whether the natural anticoagulants protein C and free protein S are reduced in active TB and whether baseline levels are associated with bacillary burden, treatment response, CT evolution, and pulmonary embolism (PE)." (PMID 41827320, 2026). "The pulmonary embolism in Case 1 could have been triggered by a previously known protein S deficiency." (PMID 32583764, 2020). "There are a few case reports of patients with concurrent deficiencies of protein C, protein S, and antithrombin III who developed massive pulmonary embolism necessitating mechanical ventilation." (PMID 40363962, 2025). "This case highlights a rare convergence of arterial ischemic stroke and pulmonary embolism (PE) in a young adult with active Graves’ disease and low Protein S, after exclusion of cardioembolic sources and systemic autoimmune conditions." (PMID 41536381, 2025). "Notably, the two patients who had low protein S activity, as well as meeting positivity criteria, were diagnosed with thrombophlebitis and pulmonary embolism (coagulation-related AEFI)." (PMID 39424883, 2024).
diabetes (20 papers, 2014 to 2026). "Maternal risk factors comprised diabetes or gestational diabetes (3/20), recurrent pregnancy losses or intrauterine fetal death (2/20), thrombus in the umbilical artery or vein (2/20), maternal infection (1/20), twin pregnancy (1/20), placental abruption (1/20), and protein S deficiency (1/20)." (PMID 39969648, 2025). "Conversely, in the PROS1 low-expression group, pathways related to bladder cancer, cytokine-cytokine receptor interactions, and youth maturity-onset diabetes were active." (PMID 38613800, 2024). "Protein S (PS) is a multifunctional glycoprotein that ameliorates the detrimental effects of diabetes mellitus (DM)." (PMID 34001977, 2021). "Although we did not exclude transgender women with comorbidities, sensitivity analyses showed no influence of prediabetes, or diabetes mellitus on the differences found in free protein S and PAI-1." (PMID 40367073, 2025).
ischemic stroke (20 papers, 2010 to 2026). A stroke disorder caused by obstruction of blood flow to the brain, due to thrombotic (local blood clot formation) or embolic (due to a blood clot or other material traveling from another site) event. "Genetic mutation of PROS1 causes various diseases, including ischemic stroke by increasing thrombosis." (PMID 32466277, 2020). "A more recent study reported annual incidences of myocardial infarction and/or ischemic stroke of 0.32% (protein S), 0.32% (protein C), and 0.21% (antithrombin) in deficient subjects and 0.19% in non–deficient subjects >20 years of age." (PMID 21254740, 2010). "The keywords factor V Leiden (FVL), factor II, prothrombin (PT), protein C (PC), protein S (PS), antithrombin (AT), ischemic stroke, and young were used to search different databases." (PMID 36360317, 2022). "In this study, we observed an increased concentration of protein S in platelet proteome in the acute phase of ischemic stroke as compared with the control." (PMID 35268287, 2022). "The role of the natural anticoagulants, antithrombin III, protein C, and protein S, in patients with ischemic stroke, remains uncertain." (PMID 30046235, 2018). "Our results indicate that the expression of PLG and PROS1 was elevated in ischemic stroke patients due to excessive blood clotting in ischemic stroke patients, which may be increased by the feedback mechanism that reduces blood clotting to maintain homeostasis." (PMID 32466277, 2020). "On the other hand, the lower protein S levels detected in our patients compared to those of the healthy controls could be an indication of an increased tendency for excessive blood clotting and may also increase the risk of VTE and ischemic stroke in patients with parathyroid adenoma." (PMID 33154484, 2020). "Some data have confirmed the relationship between reduced plasma concentration of protein S, a non-enzymatic element of hemostasis that regulates the activity of protein C, and the occurrence of ischemic stroke." (PMID 35268287, 2022).
liver disease (19 papers, 2004 to 2025). "Specifically, vitamin K deficiency, liver disease, warfarin therapy, pregnancy and hormonal therapy, nephrotic syndrome, severe infections or inflammatory states (downregulation of protein S synthesis), and FV Leiden causes false low PS levels." (PMID 40429442, 2025). "While liver disease is typically associated with bleeding risks, paradoxically, it also predisposes patients to thrombosis due to reduced synthesis of anticoagulant proteins such as protein C, protein S, and antithrombin III." (PMID 40421351, 2025). "However, under ischemic and hypoxic conditions, hepatocytes fail to produce normal amounts of the major physiological anticoagulant, protein C and its cofactor, protein S. Additionally, damage to endothelial cells in portal hypertension cause activation and consumption of these proteins." (PMID 36394820, 2022). "In liver disease, there is a decrease in the production of regulatory antithrombin, protein C, or protein S." (PMID 40845038, 2025). "Decreased activity of vitamin K-dependent proteins can be observed in liver disease, resulting from the overall decrease in protein synthesis." (PMID 39840185, 2024). "In addition to congenital mutations, oral contraceptives, pregnancy, hormone-replacement therapy, hypoxia and hepatic disorders can also decrease protein S levels." (PMID 35815065, 2021). "On the other hand, diagnosis of protein S deficiency remains a challenge due to the variable of possible genetic defects, assay performance, and various confounds such as use of oral contraceptives, surgery, infection, DIC, pregnancy/puerperium, HIV infection, and liver disease." (PMID 35815065, 2021). "Furthermore, plasma levels of factor XII and–in particular–of protein S were only moderately or not at all affected by advanced liver disease." (PMID 27171213, 2016).
coagulation disorder (18 papers, 2010 to 2025). "The etiologic factors associated with mesenteric venous thrombosis are varied, most commonly associated with coagulation disorders such as Factor V Leiden, protein C and protein S deficiencies, and antithrombin III deficiency." (PMID 24455391, 2013). "Identifying predisposing factors, such as the increased expression of CD147 and the reduction in plasmatic PROS1 levels, could be instrumental in proactively determining the risk of coagulopathies associated with SARS-CoV-2 infection and LCS." (PMID 38398746, 2024). "The observed decrease of PROS1 anticoagulant protein in SARS-CoV-2 positive biopsies strengthens the association between coagulopathies development and SARS-CoV-2 in situ presence, possibly through PROS1 impairment by proteolytic activity, carried out by SARS-CoV-2 PLpro viral protease." (PMID 38398746, 2024). "Nevertheless, the findings are noteworthy as they, for the first time, suggest a direct link between the in situ vascular presence of SARS-CoV-2 and the onset of coagulopathies, proposing an alteration in PROS1 expression as a potential key contributor to SARS-CoV-2-associated coagulation disorders." (PMID 38398746, 2024). "Among the patients that received pre-operative study for altered coagulation states, three had a known coagulation disorder (12%), two of them had protein S deficiency, while one was reported as a nonspecific prothrombotic state." (PMID 34501472, 2021). "Third, we only determined serum thrombomodulin levels and we did not analyze other biomarkers of coagulopathy or vascular injury such as protein C, protein S, ICAM-1, VCAM-1 and E-selectin." (PMID 28771554, 2017). "Coagulation disorders were ruled out in both the patients, with normal findings for aPTT and antithrombin III and activities of Protein C and Protein S level in the lower normal range." (PMID 41306813, 2025).
atherosclerosis (16 papers, 2012 to 2026). A disease characterized by the build-up of fatty material and calcium deposition in the arterial wall resulting in partial or complete occlusion of the arterial lumen. "Atherosclerosis, Behcet disease, thrombocytosis, protein S, protein C, antithrombin III deficiency, and malignancies which increase thrombotic tendency can be counted among the major etiologic factors of acute mesenteric ischemia." (PMID 23304160, 2012). "Protein S circulates in the plasma at ~350 nMand is involved in hemostasis, apoptosis, inflammation, and atherosclerosis." (PMID 39684449, 2024). "Experiments in animals lacking TIM-4, MertK, milk fat globule-EGF factor 8 protein (MFGE8), or protein S (ProS) revealed reduced AC clearance, increased inflammation, and worsened atherosclerosis." (PMID 39695119, 2024). "We then turned our attention to T cells, because activated effector T cells promote atherosclerosis progression, and T cell-derived Protein S acts on TAM receptors on dendritic cells to dampen the magnitude of the T cell response." (PMID 27958361, 2016). "However, the increase in protein S levels was attributed to the heightened, inappropriate, immune response as a result of atherosclerosis in CHD38." (PMID 38879576, 2024). "In addition, if the TAM receptor ligand Protein S were particularly important in advanced atherosclerosis, the finding that Protein S has a greater affinity for MerTK versus Axl may help explain the dominance of MerTK in this setting." (PMID 27958361, 2016). "The ligands of these receptors, Protein S (PS) and growth arrest specific protein 6 (Gas6), are essential for TAM receptor functions in the amplification and resolution of atherosclerosis." (PMID 39684449, 2024).
glioblastoma (16 papers, 2013 to 2025). The most malignant astrocytic tumor (WHO grade IV). "At the same time, Pros1 loss in glioblastoma cells decreased proliferation, cell migration, and invasion and increased apoptosis." (PMID 31636733, 2019). "In the TME of glioblastoma, immune-related cells secrete Pros1, which stimulates the proliferation of glioblastoma cells." (PMID 40088262, 2025). "By phosphorylating AXL and activating downstream NF-κB signal pathway, PROS1 promotes Glioblastoma (GBM) tumor growth." (PMID 37328828, 2023). "Aberrantly high expression of PROS1 displayed vital roles in promoting the development of glioblastoma, oral squamous cell carcinoma, and colorectal cancer." (PMID 34414029, 2021). "In glioblastoma, macrophage-derived Pros1 induced Axl phosphorylation and consequent tumor growth in an NFκB-dependent manner." (PMID 30533018, 2018). "Moreover, PROS1 has been identified as a potential target gene in several types of human cancers, including papillary thyroid carcinoma, oral squamous cell carcinoma, malignant thyroid cancer, intrahepatic cholangiocellular carcinoma, and glioblastoma." (PMID 35879775, 2022). "On the other hand, alterations of SGCG, HTR4, ITGB1, CPS1, PROS1 and INPP5A were detected predominantly in anaplastic astrocytoma, while alterations of PDE4D were present in both glioblastoma subtypes." (PMID 24358143, 2013).
Obesity (16 papers, 2014 to 2025). Accumulation of substantial excess body fat. "This study reveals how estrogen and obesity together reduce Protein S levels, increasing blood clot risk in premenopausal women using hormonal contraceptives." (PMID 41243971, 2025). "Hereditary risk factors for VTE include Factor V Leiden, Prothrombin G20210A, and deficiency in protein S, protein C, or antithrombin, whereas some therapies and many disorders (e.g., heart failure, obesity, pregnancy) are acquired risk factors." (PMID 38248552, 2024). "Protein S (PS), an essential anticoagulant cofactor, is downregulated by both estrogen and obesity, but the molecular basis for this suppression remains poorly defined." (PMID 41243971, 2025). "Over the last few decades, studies concerning PROS1 have focused mainly on its involvement in human cardiovascular disease, with few reports mentioning the role of PROS1 in obesity." (PMID 36009634, 2022). "In HepG2 hepatocytes, hypoxic conditions (1%–10% O2) mimicking obesity, with or without 17 β-estradiol, suppressed PROS1 transcription and promoter activity." (PMID 41243971, 2025).
pancreatic cancer (16 papers, 2005 to 2025). "Bulk EV isolated from blood followed by glypican‐1 protein single‐marker analysis can identify early‐stage pancreatic cancer; EV subtypes isolated using antibody cocktails that target EV surface proteins showed higher specificity for pancreatic cancer compared to single‐marker isolation." (PMID 30975688, 2019). "An early study investigating the haemostatic balance in pancreatic cancer found that the coagulation inhibitors antithrombin III, heparin cofactor II, protein C, free protein S, and thrombomodulin were significantly decreased during the progression of pancreatic cancer after diagnosis." (PMID 30314362, 2018).
Thromboembolism (15 papers, 2005 to 2025). The formation of a blood clot inside a blood vessel that subsequently travels through the blood stream from the site where it formed to another location in the body, generally leading to vascular occlusion at the distant site. "Our proteomics data suggest that ProS1, another cofactor necessary for the inactivation of factors Va and VIIIa and whose deficiency is linked to thromboembolism, was deregulated in SHR animals." (PMID 36014793, 2022). "Plasma levels of the anticoagulant cofactor protein S and PROS1 mutation are reported to impart increased risk of thromboembolism in European and south east Asian populations, but the relationship is not yet documented in Han Chinese in population-based study." (PMID 35815065, 2021). "Although fresh frozen plasma, rich in protein S, is often used in cardiac surgery for protein S deficiency patients, the most appropriate times and volume of its administration to prevent thromboembolism remain poorly understood." (PMID 29492451, 2018). "A mutation in the domain causes thromboembolic disease due to protein C deficiency, matching the fact that defects in PROS1 are also associated with an increased risk of thrombotic disease (Uniprot:P07225)." (PMID 17868464, 2007). "Protein S deficiency and intracardiac devices also increased the risk of thromboembolism." (PMID 34273971, 2021). "Among the familial thromboembolism cases, 14% - 24% is found to be related to AT III, protein C or protein S deficiency." (PMID 27942288, 2010). "Although the underlying mechanism of the higher protein S levels in ONFH is not clear, it is possible that the elevated protein S and anti-thrombin III levels may be secondary to or associated with endothelial dysfunction and intraosseous thromboembolism." (PMID 36078892, 2022).